IL4 (interleukin 4)
Diseases named in the same sentence as IL4 in open-access papers (continued):
Sharing a sentence is not in itself a finding about the gene and the disease.
lupus (62 papers, 2008 to 2026). "This phenotype was associated with a still significant constitutive IL-6 production by IL-4-deficient basophils in the lupus-like context." (PMID 38649353, 2024). "This was associated with a dramatic decrease in kidney IL-4 and IL-1β pro-inflammatory cytokines concentrations as we previously demonstrated in the Lyn−/− lupus-like model." (PMID 28801578, 2017). "Global over-expression of IL-4 in the C3H mouse strain resulted in elevated serum IgG levels and autoimmune glomerulonephritis while IL-4 deficient lupus prone mice had improved disease." (PMID 24040398, 2013). "Additionally, programmed death-ligand 1 (PD-L1) and IL-4-producing basophils further help pathogenic Tfh accumulation in lupus." (PMID 41283475, 2025). "The exact role of IL-4 in causing damage to the glomeruli is still a matter of debate, but it is known to play a role in several cases of systemic lupus erythematosus (SLE) and immunoglobulin A (IgA) nephropathy." (PMID 39830109, 2024). "Furthermore, cell death may promote the release of DNA and associated self-antigens, leading to the IL-4 dependent generation of IgE-specific autoantibodies, as described in systemic lupus erythematosus." (PMID 29922282, 2018). "In animal experiments, both the MSCs treatment group and the 17‐AAG group exhibited lower serum and supernatant levels of IL‐4 compared to lupus model mice." (PMID 40801323, 2025). "In lupus-prone mice, IL-4 levels are elevated and can drive IgG-to-IgE class switching, though human studies show more variable results." (PMID 41283475, 2025). "Estrogens generally enhance humoral autoimmunity and stimulate the T-cell response typical of lupus, leading to increased production of cytokines such as IL-4, IL-5, IL-10, and IL-13." (PMID 40283389, 2025). "In lupus-prone mice, blocking IL-4 decreases anti-double-stranded DNA (anti-dsDNA) antibodies, whereas the administration of IL-4 increases the levels of this autoantibody." (PMID 39975551, 2025). "Conversely, studies have also found that in systemic lupus erythematosus (SLE), loss of PGRN reduces Th1, Th17, IFN-γ, and IL-17A levels, whereas it increases Th2, Treg, Breg, IL-4, and IL-10 levels." (PMID 40290306, 2025). "Studies have demonstrated that in lupus‐prone mice, IL‐4 contributes to the skewing of immune responses toward autoantibody production, further aggravating the disease." (PMID 40491969, 2025). "GATA3 TF expression, IL-4 production, and potent help provided to B cells characterize the TFH type 2 (TFH2) cell subset, which is overrepresented in the context of lupus and associated with disease activity." (PMID 38649353, 2024). "Second, the same observations were done concerning IL-4 production by TFH cells showing a TFH2 bias in these two lupus-like models, as also observed in the SLE patient cohort." (PMID 38649353, 2024). "Both the lupus-like context in vivo and the co-culture system in vitro induced IL-4 and IL-6 production by basophils." (PMID 38649353, 2024). "In studies about systemic lupus erythematosus, IL-4 has been found to promote inflammatory responses in target organs, increase production of IgG and IgE, and is an essential inflammatory factor in the disease." (PMID 37391717, 2023). "Consistent with the findings in the scleroderma-like cGVHD model, we found that the frequencies of TNF-ɑ-and IL-4-expressing CD4+T cells were significantly increased in the spleens of lupus-like recipients with IL-39 plasmid treatment." (PMID 35655245, 2022). "GDF-15 treatment significantly reduced levels of IL-1β, IL-2, IL-4, IL-21, and IL-22, by which treatment of lupus mice with 100 μg/kg GDF-15 had the most efficiency." (PMID 35911685, 2022). "Pristane-induced lupus mice showed significantly higher serum levels of IL-1β, IL-2, IL-4, IL-13, IL-21, and IL-22 compared to those in WT mice." (PMID 35911685, 2022).
lupus (continued). "Abnormal methylation of T cells in SLE patients leads to overexpression of methylation-sensitive autoimmune genes CD70, ITGAL (integrin subunit alpha L) (CD11a), selectin-1, IL-4, and IL-13 in lupus." (PMID 33859701, 2021). "Basophil activation and IL-4 secretion drives B cell class switching towards IgE and autoreactive IgE is recognized as an important inducer of lupus pathogenesis." (PMID 29463843, 2018). "The lupus mice exhibited a significant elevation in plasma levels of IL-4, IL-6, IL-7, IL-12, IL-17, IFN-α, IFN-γ, TGF-β, BAFF and APRIL and a marked elevation of IgG2a, IgG3 and ant-dsDNA autoantibodies compared with normal healthy mice." (PMID 25909640, 2015). "For IL-4 polymorphism haplotypes, previous experimental data has demonstrated some to be associated with respiratory syncytial virus, multiple sclerosis, oral cancer, and systemic lupus erythematosus, suggesting that certain important polymorphisms could affect the regulation of this cytokine." (PMID 25295591, 2014). "However, it strongly suggests as well that basophil-derived IL-4 is mandatory for autoantibody class switch towards IgG in the lupus-like context." (PMID 38649353, 2024). "We next assessed whether IL-3 or IL-4 blockade could modulate in vivo the PD-L1 expression on the surface of basophils in the lupus-like context of Lyn–/– mice." (PMID 38649353, 2024). "IL-4 and IL-13, both induced by type 2 immune responses, were overexpressed in lupus mice." (PMID 35911685, 2022). "The upregulated IFIT1 in lupus plays an important role in the production of cytokines IL-4 and IL-10, which may be related to the imbalance of Th1/Th2." (PMID 30836987, 2019). "FWGE has been reported to increase blastic transformation of peripheral blood T cells by concanavalin A, to reduce graft survival in a coisogenic skin transplantation model and to reduce production of IL-4 and IL-10 in a systemic lupus erythematosus model, supporting its immunomodulatory properties." (PMID 29304125, 2018). "Lupus-associated and inflammatory cytokine genes, such as IL4, IL6, IL10 and IL13, are demethylated in lupus T cells and may contribute to disease progression." (PMID 25988383, 2015). "Our results suggest that IL-4 could inhibit the TLR7-9 pathogenic steps and decrease the production of the IFN Signature in lupus." (PMID 24489947, 2014). "We further examined the mechanisms by which FLI1 may be controlling TCR-specific activation and IL-4 production in lupus T cells." (PMID 24040398, 2013). "In summary, our results demonstrate a role for FLI1 in regulating lupus T cell activation and IL-4 production through modulation of glycosphingolipid metabolism, specifically by mediating the breakdown pathway through the control of Neu1 expression and/or NEU activity during early disease." (PMID 24040398, 2013). "These disparities appear to arise, at least in part, from variations in the cytokines that are secreted by the NKT cells in the different lupus mouse models, with interleukin-4-secreting NKT cells inhibiting lupus and interferon-γ-secreting NKT cells exacerbating lupus." (PMID 18783591, 2008). "Furthermore, dupilumab’s blockade of IL-4 and IL-13 may be ineffective, or even detrimental, in Th1-related disorders like systemic lupus erythematosus (SLE), potentially accelerating disease progression." (PMID 40151702, 2025). "Our results indicate that the pathogenic accumulation of TFH cells in SLO in lupus and thus spontaneous TFH cell responses, are fully dependent on SLO-localized basophils (mainly at the T:B border) and more precisely mediated by basophil expression of PD-L1 and IL-4." (PMID 38649353, 2024). "Together with the PD-L1 overexpression by blood basophils from SLE patients, these results strongly suggest that, as demonstrated in the lupus-like mouse models, basophils promote the pathogenic accumulation of TFH and TFH2 cells during SLE pathogenesis through their expression of PD-L1 and IL-4." (PMID 38649353, 2024).
lupus (continued). "SLE has been considered a disease in which Th2 cytokines, such as IL-4, predominate; however, among SLE patients with moderate to severe lupus nephritis, Th1-dominant immune responses." (PMID 38072921, 2023). "Finally, IL-4 may be beneficial in blocking the recognition of self-adjuvants and self-antigens in systemic lupus erythematosus." (PMID 24489947, 2014). "Through PD-1/PD-L1 dependent mechanisms and IL-4 production, basophils controlled TFH cell numbers, cytokine production abilities, TF expressions, and TFH cell functions in the lupus context." (PMID 38649353, 2024). "Our data suggest that basophils deliver the required IL-4-induced priming to CD4+ T cells in a PD-L1-dependent manner that allows TFH and TFH2 cell accumulations in the lupus-like context." (PMID 38649353, 2024). "Accordingly, systemic IL-4 blockade dampened TFH2 cell accumulation and their deleterious effects in the Ets1ΔCD4 lupus-like mouse model." (PMID 38649353, 2024). "Vitamin E has antioxidant and anti-inflammatory effects and, because of its anti-inflammatory effect, seeks to reduce IL-2, IL-4, and TNF-α, which can be effective in lupus." (PMID 37511964, 2023). "In the early stages of lupus, the M1 pathway is mediated by cytokines including IFN-γ, whereas the M2 pathway is mediated by IL-4 and IL-13." (PMID 35733860, 2022). "Percentages of CD8+, CD11b+, CD19+, CD11C+ cells, TH2 cells, and pro-inflammatory cytokines (IL-1β, IL-2, IL-4, IL-21, and IL-22) were reduced after GDF-15 treatment in lupus mice." (PMID 35911685, 2022). "In our present study, based on mice models, we found that GDF-15 alleviated lupus by reducing renal damage, reversing CD8+, CD19+, and TH2 cells dysregulation, inhibiting production of IL-1β, IL-2, IL-4, IL-21, IL-22, ANA, and total IgG." (PMID 35911685, 2022). "In humans, some studies showed increased IL-4, but decreased IFN-γ in lupus patients, whereas others indicate the importance of IFN-γ in diffuse proliferative lupus nephritis." (PMID 33763079, 2021). "Interestingly, at around 40 weeks, Lyn−/− mice develop IgE- and IL-4-dependent lupus-like nephritis, with glomerular deposition of circulating immune complexes (CICs) and autoimmune manifestations that resemble human SLE." (PMID 32977704, 2020). "We observed that lupus mice had aberrant and significantly elevated levels of IL-4, IL-6, IL-7, IL-12, IL-17, IFN-α, IFN-γ, TGF-β, BAFF and APRIL compared with the control non-lupus healthy mice (* P < 0.05)." (PMID 25909640, 2015). "Our findings revealed increased levels of IL-4, IL-6, IL-7, IL-12, IL-17, IFN-α, IFN-γ, TGF-β, BAFF and APRIL in lupus mice." (PMID 25909640, 2015). "Together, our results suggest reducing FLI1 in lupus decreases the pathogenicity of T cells by decreasing TCR-specific activation and IL-4 production in part through the modulation of glycosphingolipid metabolism." (PMID 24040398, 2013). "We found that Gal-9 decreased the frequency of Th1 (IFNγ+ IL-4− CD3+ CD4+ cells) significantly, while Th2 (IL-4+ IFNγ− CD3+ CD4+ cells) were unchanged in Gal-9-treated MRL/lpr lupus-prone mice." (PMID 23585851, 2013). "Although early reports demonstrated defective Th1 and excessive Th2 responses in lupus, recent data suggest that the levels of both Th1 (IFN-γ, IL-12, and IL-18) and Th2 (IL-4, and IL-10) cytokines are increased in the sera of lupus patients." (PMID 22761630, 2012). "In systemic lupus erythematosus (SLE), DN T cells reactive to CD1c can produce IL-4 and IFN-γ, and may support IgG production by CD1c+ B cells." (PMID 40709176, 2025). "In lupus-prone MRL/lpr mice, IL-4 signaling impairs apoptosis of autoreactive B cells." (PMID 41280899, 2025). "Unlike what was observed in basophils from control mice, constitutive IL-4 and IL-6 productions were significantly detected in non-restimulated basophils from both lupus-like models, whereas no major differences were noticed after PMA-ionomycin restimulation." (PMID 38649353, 2024).
lupus (continued). "Altogether, these results strongly suggest that the increased IL-3 and IL-4 titers sustain basophil activation and accumulation in SLO in the lupus-like context where they promote their PD-L1 and IL-4-dependent effects on TFH cell and plasmablast accumulations." (PMID 38649353, 2024). "Third, basophil depletion dramatically dampened both constitutive and PMA-ionomycin-induced IL-21 and IL-4 productions by TFH cells only in the lupus-like context, without significantly influencing their IFNγ or IL-17A production abilities." (PMID 38649353, 2024). "Altogether, these results strongly suggest that in the lupus-like context basophils in SLO enable TFH cell accumulation, increase TFH cell ability to produce IL-21 and IL-4 and promote TFH cell function including B cell isotype switch and plasmablast differentiation." (PMID 38649353, 2024). "High levels of IL-4, IFN-ɣ, and IL-17 were determined in the P–C group, as corroborated by researchers in lupus conditions, who reported that high-level expression of IFN-ɣ, IL-17 in lupus-like disease could contribute to the tissue damage." (PMID 38072921, 2023). "In contrast to mTORC2, increased activation of mTORC1 is observed in CD4+ T cells obtained from SLE patients and lupus prone mice leading to elevated IL-17, IL-4 producing double negative T cell expansion and regulatory T cell (Treg) depletion." (PMID 32257420, 2020). "In the known mouse models of spontaneous lupus, MRL/lpr mice develop similar pathological reactions to that of SLE patients, like renal damage as well as abnormal horizontal expression of cytokines IL-2, IL-4, IL-17, and TNF-α." (PMID 31781262, 2019). "Therefore, we monitored the proliferative capacity of B cells in response to IL-4 and CD40L in the three experimental lupus groups as well as in the non-lupus control mice using CFSE assays and flow cytometry analysis." (PMID 25909640, 2015). "Our data revealed amelioration of BTN3A1‐induced lupus‐like changes, such as improved degree of renal injuries and reduced percentage of CD3+, CD8+ T cells, Th1, Th2, Th17 cells, upregulated percentage of Treg cells, and lower expression of IL‐4, IL‐6, IL‐10, IL‐17A, IFN‐γ, TNF‐α, and dsDNA." (PMID 40959207, 2025). "Since TFH cell differentiation ex vivo depended on IL-4 expression by basophils, we next sought to verify whether basophil-derived IL-4 was mandatory for the basophil-TFH cell functional relationship in the lupus-like context." (PMID 38649353, 2024). "IL2/IL4 and IL2/IL10 ratios have been repeatedly used as markers of inflammation and tissue injury in Systemic Lupus Erythematosus (SLE), or as an indication of cytokine imbalance in vitiligo, also in athletes." (PMID 34271953, 2021). "For MRL/lpr lupus mice that received treatment, the pathological damage of the kidneys was significantly improved; the serum levels of IL-4 and IFN-γ were decreased; and the mechanism of JP on SLE was studied from the perspective of DNA methylation regulation." (PMID 31781262, 2019). "Together, our results in the T cells from early disease lupus mice suggest FLI1 controls directly or indirectly the transcription of Neu1 such that reduction of FLI1 leads to decreased Neu1 expression/activity leading to decreased TCR-specific activation and IL-4 production." (PMID 24040398, 2013). "Moreover, PD-L1 expressing basophils that did not express IL-4 could induce TFH cell- and GC B cell-independent expansion of plasmablasts in lupus models, indicating that basophils, through PD-L1 expression, had a significant impact as well on the EF response." (PMID 38649353, 2024).
gastric cancer (57 papers, 2002 to 2025). A primary or metastatic malignant neoplasm involving the stomach. "In summary, this study takes the lead in finding that IL-4 is associated with immunotherapy resistance in gastric cancer, and to reveal the molecular mechanism of the metabolic reprogramming of macrophages mediated by IL-4." (PMID 39003253, 2024). "In our study, using multivariable logistic regression, having adjusted for the potential confounders of age, gender, and ethnicity, revealed an estimated 76 and 63% increased risk of gastritis and gastric cancer in IL-4 -590T carriers, respectively." (PMID 27677314, 2017). "Here, we have targeted IL-4 C-590T SNP, since previous reports from Asian populations have demonstrated a risk impact for gastric cancer in IL-4 -590T carriers, in reference to the wild genotype." (PMID 27677314, 2017). "In contrast the present study revealed an association between gastric cancer and IL4 VNTR polymorphism." (PMID 26383107, 2015). "Moreover, postoperative complications were associated with increased Th1 cells and reduced IL-4 in elderly gastric cancer patients." (PMID 36386524, 2022). "In the collinearity analysis, we annotated the function of the coexpression gene network module and compared the gene association changes of the subnetwork modules including interleukin-4 and interleukin-13 signaling pathway in normal samples and gastric cancer samples." (PMID 32832545, 2020). "Higher levels of IL4, IL4Ra, and IL13Ra1 mRNA expression were detected in gastric than colorectal cancer, which, taking into account their association with tumor progression and aggressiveness may contribute to worse prognosis associated with gastric cancers." (PMID 32512917, 2020). "When studying IL-4, an increase in this indicator was found in patients with gastric cancer at stages I, II, and III of the disease compared to the control group and the group of patients at stage IV of the disease (p1–2 < 0.001, p1–3 < 0.001, p1–4 < 0.001)." (PMID 40806737, 2025). "In‐vivo immunomodulatory effect on gastric cancer rats: Promotes splenocyte proliferation and improves anti‐inflammatory cytokines (IL‐2, IL‐4, and IL‐10) secretion." (PMID 41211514, 2025). "When studying this cytokine in patients with stage IV gastric cancer, a decrease in IL-4 was found compared to the control group (p1–5 = 0.03, p2–5 < 0.001, p3–5 < 0.001, p4–5 < 0.001)." (PMID 40806737, 2025). "In gastric cancer, cyclase-associated protein 2 (CAP2) bound to RACK1 and activated the SRC/FAK/ERK signaling pathway, leading to IL-4 and IL10 secretion, and M2 macrophage polarization." (PMID 38315284, 2024). "Among these 14 cytokines, the expression of IL-4 was the most significantly upregulated in gastric cancer patient resistance to anti-PD1 therapy compared to the sensitive group." (PMID 39003253, 2024). "Monocyte-derived macrophages stimulated by IL-4 were co-cultured with T cells (PBMC derived T cells from gastric cancer patients, Lymphocytic leukemia cell line Jurkat cells activated by T cell Activator)." (PMID 39003253, 2024). "After binding to its receptor, IL-4 and IL-13 can mediate tumor cell proliferation, survival, and metastasis in colorectal and gastric cancers." (PMID 35432477, 2022). "Increased as well as decreased levels of IL-4 and IL-10 have been reported in esophageal and gastric cancers and their prognostic value remains uncertain." (PMID 32298379, 2020). "In a high-risk gastric cancer (GC) region, a previous study suggested that rs2070874 C allele in the IL-4 gene might decrease the susceptibility to GC in a Chinese population." (PMID 32744314, 2020). "Th2 T-cell response, represented by IL4, plays a protective role in the development of gastric cancer." (PMID 26383107, 2015). "Several epidemiological studies have examined the association between the IL4 VNTR polymorphism and the risk of cancer, including prostate, urothelial, breast, colorectal, and gastric cancers but the results are inconsistent." (PMID 26383107, 2015).